USP5 (ubiquitin specific peptidase 5)
Diseases named in the same sentence as USP5 in open-access papers (continued):
Sharing a sentence is not in itself a finding about the gene and the disease.
lung adenocarcinoma (3 papers, 2020 to 2022). A carcinoma that arises from the lung and is characterized by the presence of malignant glandular epithelial cells. "Together, these findings suggest that the USP5-Beclin 1 pathway plays a critical role in lung adenocarcinoma development." (PMID 36528652, 2022).
lymph node metastasis (3 papers, 2020 to 2025). "Additionally, high USP5 levels were strongly linked to lymph node metastasis, suggesting a more aggressive disease phenotype." (PMID 40066708, 2025). "The expression of USP5 was not related to gender, age, lymph node metastasis, pathological grade, the EGFR mutation and ALK translocation but was related to tumor size, and the difference was statistically significant." (PMID 36611139, 2023). "Interestingly, the results showed that the expression of USP5 was elevated in patients with lymph node metastasis." (PMID 33123271, 2020).
ovarian carcinoma (3 papers, 2019 to 2023). A malignant neoplasm originating from the surface ovarian epithelium. "Considering the association between USP5 and HDAC2, we hypothesized that USP5 amplification may affect the sensitivity of ovarian cancer cells to HDAC inhibitor." (PMID 31727867, 2019). "As ubiquitin-specific peptidase 5 has been shown to promote ovarian cancer cell proliferation, 2c can represent a possible new treatment for EOC." (PMID 37108391, 2023). "USP5 overexpression increased the sensitivity of ovarian cancer cells to HDAC inhibitor PXD101, which was reversed by HDAC2 knockdown." (PMID 31727867, 2019). "We examined the USP5 protein levels in five ovarian cancer cell lines and a normal human ovarian cell line IOSE80." (PMID 31727867, 2019). "Western blotting analysis showed that the most affected Class I HDAC member in ovarian cancer cells with USP5 knockdown was HDAC2." (PMID 31727867, 2019). "Disruption of USP5 profoundly repressed cell proliferation by inducing cell cycle G0/G1 phase arrest in ovarian cancer cells." (PMID 31727867, 2019). "We found that ovarian cancer cells with USP5 amplification was more sensitive to PXD101-induced apoptosis than those without USP5 amplification." (PMID 31727867, 2019). "HDAC2 knockdown partially abrogated USP5-promoted ovarian cancer cell proliferation." (PMID 31727867, 2019). "Following USP5 shRNAs (#1 and #2) transduction, the proliferation of both cancer cell lines was determined using CCK-8 assays, which showed that down-regulation of USP5 caused profoundly reduced proliferation of both ovarian cancer cell lines (P<0.001)." (PMID 31727867, 2019). "USP5 knockdown significantly induced G0/G1 arrest in ovarian cancer cells." (PMID 31727867, 2019). "Two ovarian cancer cell lines, OVCAR3 and CAOV3, showed the highest protein expression of USP5, while SKOV3 had similar USP5 expression as IOSE80 cells." (PMID 31727867, 2019). "To explore the functional relevance of the upregulation of USP5 in ovarian cancer cells, we used lentivirus-mediated shRNAs to knock down USP5 expression in OVCAR3 and CAOV3 cells, which expressed relatively high levels of USP5." (PMID 31727867, 2019). "Thus, we speculate that USP5 may be a deubiquitinase of HDAC2, which negatively regulated the expression of p27 and p21 and led to the accelerated cell cycle transition and cell proliferation in ovarian cancer cells." (PMID 31727867, 2019).
acute myeloid leukemia (2 papers, 2025). Acute myeloid leukemia (AML) is a group of neoplasms arising from precursor cells committed to the myeloid cell-line differentiation. "Further analysis using the pan‐cancer database revealed USP5 overexpression in 18 out of 23 cancer types, except for acute myeloid leukemia (AML) and skin cancer, when compared with normal tissues." (PMID 40066708, 2025).
cardiomyopathy (2 papers, 2023 to 2025). A disease of the heart muscle or myocardium proper. "Nevertheless, extensive further research is necessary to determine whether forced or induced expression of USP5 improves clinical manifestations of cardiomyopathy." (PMID 39841822, 2025).
ductal adenocarcinoma (2 papers, 2017 to 2020). "The mRNA expression of USP5 was significantly up‐regulated in ductal adenocarcinoma tissues than in pancreatic ductal tissues." (PMID 31845546, 2020). "A modest increase in USP5 mRNA expression was already evident in chronic pancreatic tissues as compared to the healthy tissues, while ductal adenocarcinoma tissues showed significant over-expression of USP5 compared to both chronic pancreatitis as well as healthy pancreatic tissues." (PMID 29029505, 2017).
Lewis lung carcinoma (2 papers, 2021 to 2024). "In addition, knockdown of USP5 retarded tumor growth in the Lewis lung carcinoma mouse model." (PMID 34741014, 2021). "T cells were isolated from mouse Lewis lung carcinoma (LLC)-bearing mice and then stimulated with concanavalin A before co-cultured with LLC cells transfected with USP5 siRNA or USP5 siRNA plus Flag tagged mouse PD-L1 (Flag-mPD-L1)." (PMID 34741014, 2021).
lymphoma (2 papers, 2022 to 2023). A malignant (clonal) proliferation of B- lymphocytes or T- lymphocytes which involves the lymph nodes, bone marrow and/or extranodal sites. "To this end, we used the shRNA to knockdown Usp5 expression in mouse E.G7-OVA lymphoma cells and confirmed that knockdown of Usp5 dramatically reduced PD-1 protein expression in E.G7-OVA cells." (PMID 37208329, 2023). "USP5/IsoT, USP7/HAUSP, USP9, and USP15i are higher expressed in EBV-transformed lymphoblastoid cell line (LCL) than in the Burkitt’s lymphoma cell line Raji." (PMID 35158879, 2022).
periodontitis (2 papers, 2024 to 2025). An acute or chronic inflammatory process that affects the tissues that surround and support the teeth. "Research has revealed that compared to healthy controls, patients with chronic periodontitis exhibited elevated USP5 protein levels in both the gingival sulcus fluid and gingival tissues." (PMID 39626954, 2025). "Mechanistically, the knockdown of USP5 prevented the phosphorylation and activation of STAT3, effectively inhibiting LPS‐induced inflammatory responses in PDLSCs, indicating that targeted suppression of USP5 provides advantageous outcomes in mitigating periodontitis." (PMID 39626954, 2025). "It has been reported that USP5 is upregulated in the gingival crevicular fluid and gingival tissues of patients with periodontitis, showing a positive correlation with proinflammatory factors through the STAT3 signaling pathway, which exacerbates the inflammatory response in chronic periodontitis." (PMID 38322269, 2024). "Furthermore, a positive association has been established between USP5 overexpression and enhanced production of pro‐inflammatory cytokines, including TNF‐α, IL‐6 and IL‐1β in PDLSCs, suggesting that USP5 triggered inflammation and consequently aggravated periodontitis." (PMID 39626954, 2025). "Recent studies have shed light on the contrasting roles of USP5 and CYLD in periodontitis, offering potential avenues for therapeutic interventions." (PMID 38322269, 2024).
Salmonella Infections (2 papers, 2015 to 2025). Infections with bacteria of the genus SALMONELLA. "Notably, USP5 expression was strongly correlated with the mTOR signaling pathway, nonalcoholic fatty liver disease, and salmonella infection." (PMID 40066708, 2025).
viral infection (2 papers, 2021 to 2025). "Conversely, USP5 deficiency facilitated the virus infection-triggered transcription of IFNB, ISG54, and CCL5." (PMID 39761299, 2025). "In conclusion, our findings demonstrate that USP5 is downregulated during host immunity against viral infection in an IFNAR-dependent manner." (PMID 39761299, 2025). "First, we analyzed the production of IFNB, ISG54, and CCL5 in USP5-overexpressed and USP5-/- A549 cells after viral infection." (PMID 39761299, 2025). "Consistently, USP5 expression was markedly suppressed upon viral infection." (PMID 39761299, 2025). "Notably, although DUBs including OTUD1, USP5, and USP7 function to cleave K48-linked polyubiquitin chains of various substrates, the three DUBs exert opposite effects, which play negative roles in the host immune response against virus infection." (PMID 34707613, 2021).
Arthritis (1 paper, 2025). Inflammation of a joint. "Arthritis scores and paw thickness were measured to further assess the effect of USP5 on RA severity, revealing that USP5 knockdown significantly reduced arthritis severity compared to the RA model group." (PMID 41339332, 2025).
bladder tumour (1 paper, 2024). "The results demonstrated that USP5 potentially promotes bladder tumour growth." (PMID 38229092, 2024).
cardiac hypertrophy (1 paper, 2025). "Together, our findings suggest that CM-specific overexpression of USP5 reduces pressure overload–induced cardiac hypertrophy and promotes clearance of protein aggregates, thereby reducing activation of autophagic responses." (PMID 39841822, 2025). "This view is supported by the ability of USP5 to attenuate pressure overload–induced cardiac hypertrophy and prevent or revert formation of protein aggregates occurring in titinopathy and desminopathy models." (PMID 39841822, 2025). "We demonstrated that inactivation of Usp5 in mouse CMs leads to accumulation of protein aggregates and DCM, whereas increased levels of hUSP5 in CMs attenuate pressure overload–induced cardiac hypertrophy and promote clearance of protein aggregates." (PMID 39841822, 2025).
colitis (1 paper, 2025). Inflammation of the colon. "This disruption of USP5-mediated STAT3 stability led to increased STAT3 ubiquitination, reduced STAT3 expression, and ultimately inhibited the progression of colitis-associated cancer transformation." (PMID 41281755, 2025).
Desminopathy (1 paper, 2025). "Next, we wanted to know whether USP5 exerts similar effects in specific proteinopathies, such as titinopathy and desminopathy." (PMID 39841822, 2025). "Overexpression of hUSP5 restored levels of the autophagy marker p62 and normalized the LC3I/II ratio, indicating that overexpression of USP5 in CMs alleviates protein aggregation and various aspects of PQC in desminopathy, before the onset of DCM." (PMID 39841822, 2025).
diabetic (1 paper, 2015). "Our observations with the Tat-Cav3.2-III-IV peptide thus suggest that targeting Cav3.2 deubiquitination by USP5 is a potential new target for therapeutic approaches to pain hypersensitivity in diabetes and pain conditions associated with inflammatory disorders of the gut." (PMID 25889575, 2015). "Altogether, these data show that the USP5-mediated dysregulation of Cav3.2 channels occurs during both diabetic neuropathic pain and during chemically-induced visceral pain, and disrupting this process mediates analgesia." (PMID 25889575, 2015).
heart failure (1 paper, 2025). Inability of the heart to pump blood at an adequate rate to meet tissue metabolic requirements. "Together, the analysis uncovered pathological alterations in Usp5-deficient CMs, associated with rapid progression from DCM to heart failure in cKO mice." (PMID 39841822, 2025). "We demonstrate that CM-specific inactivation of Usp5 causes DCM and lethal heart failure in mice." (PMID 39841822, 2025).
injury (1 paper, 2015). Damage inflicted on the body as the direct or indirect result of an external force, with or without disruption of structural continuity. "We recently reported that USP5-mediated deubiquitination of Cav3.2 channels in mouse dorsal root ganglia and dorsal horns is enhanced following peripheral inflammation or nerve injury, leading to increased T-type calcium currents that in turn give rise to pain hypersensitivity." (PMID 25889575, 2015).
keloid (1 paper, 2016). An irregularly shaped, elevated mark on the skin caused by deposits of excessive amounts of collagen during wound healing. "PTB knockdown significantly slowed the proliferation of keloid fibroblasts and accelerated the regression of transplanted keloid tissues, which was accompanied by a shift in the alternative splicing of USP5 and RTN4." (PMID 27897224, 2016). "Our data have demonstrated that inhibited proliferation of keloid fibroblasts due to the suppression of PTB is accompanied with the alternate splicing of USP5 and RTN4, which may be correlated to over proliferation of fibroblasts in keloid." (PMID 27897224, 2016).
monoclonal gammopathy (1 paper, 2017). A condition characterized by the abnormal presence of monoclonal immunoglobulins in the blood or urine. "The mRNA levels of USP5 was markedly increased in malignant plasma cells including MM, plasma cell leukemia (PCL) and smoldering myelomas (SMM), in contrast, its expression was relatively low in patients of monoclonal gammopathy of undetermined significance, the early stage of MM." (PMID 28933784, 2017).
neuroblastoma (1 paper, 2021). Neuroblastoma (NB) is the most common solid, extracranial childhood tumor. "High mRNA expression of USP5 had a strong association with poor neuroblastoma patient prognosis in publicly available R2 gene expression datasets (n = 469 for Kocak dataset and n = 498 for SEQC dataset) for the MYCN-amplified patient subsets." (PMID 33658627, 2021). "Therefore, we investigated whether the combination treatment increased the levels of Lys48-linked polyubiquitination in neuroblastoma cells through downregulation of USP5." (PMID 33658627, 2021). "Combination therapy with an HDAC inhibitor (SAHA) and a novel pyridobenzimidazole (SE486-11) bound and inactivated USP5 with potent inhibition of tumorigenicity as a novel therapeutic approach for the treatment of MYCN-driven neuroblastoma." (PMID 33658627, 2021). "To determine the effects of USP5 suppression on neuroblastoma cells, we transiently transfected neuroblastoma cell lines with two USP5-specific siRNAs." (PMID 33658627, 2021). "Overexpression of USP5 rescued neuroblastoma cells from the cytopathic effects of the combination and reduced unanchored polyubiquitin, suggesting USP5 is a therapeutic target of the combination." (PMID 33658627, 2021). "Our results suggest USP5 protects MYCN protein from ubiquitin-mediated degradation by lowering unanchored polyubiquitin chain levels in neuroblastoma cells, an effect which can be reversed by direct binding of both drugs to USP5." (PMID 33658627, 2021). "Indeed CRISPR/Cas-9 cancer dependency screens have recently identified neuroblastoma cells to have dependency on USP5." (PMID 33658627, 2021). "We next examined whether USP5 expression levels had prognostic significance in primary tumour tissue from neuroblastoma patients." (PMID 33658627, 2021). "We found USP5 was located in both the nucleus and cytoplasm of MYCN-amplified neuroblastoma cells lines, whereas MYCN was predominantly located in the nucleus." (PMID 33658627, 2021). "We have shown that USP5 and MYCN directly interact in untreated neuroblastoma cells and, that combination therapy lowered USP5 and MYCN protein levels." (PMID 33658627, 2021). "MYCN bound to the USP5 promoter and induced USP5 gene expression suggesting that USP5 and MYCN expression created a forward positive feedback loop in neuroblastoma cells." (PMID 33658627, 2021). "Here we show that the deubiquitinase, USP5, has an important role in maintaining MYCN stability through effects on unanchored polyubiquitin levels in neuroblastoma cells." (PMID 33658627, 2021). "First, we show that in neuroblastoma cells MYCN and USP5 together stimulate a forward feedback expression loop maintaining high expression of each protein." (PMID 33658627, 2021). "Combination drug treatment with SAHA and SE486-11 reduced MYCN, USP5 and PCNA (proliferation marker) protein levels in neuroblastoma-bearing MYCN;GFP zebrafish compared to DMSO treated controls." (PMID 33658627, 2021). "Thus, USP5 acts as an oncogenic cofactor with MYCN in neuroblastoma and the novel combination of HDAC inhibitor with SE486-11 represents a novel therapeutic approach for the treatment of MYCN-driven neuroblastoma." (PMID 33658627, 2021).
neuropathy (1 paper, 2018). A disorder affecting the nervous system that manifests with pain, tingling, numbness, and/or muscle weakness. "During neuropathy and peripheral inflammation, Cav3.2 channels are upregulated due to an increased association with the deubiquitinase USP5." (PMID 30340616, 2018).
osteoarthritis (1 paper, 2020). A noninflammatory degenerative joint disease occurring chiefly in older persons, characterized by degeneration of the articular cartilage, hypertrophy of bone at the margins and changes in the synovial membrane. "Expression of USP5 was found upregulated in RA-FLS compared with that in osteoarthritis- (OA-) FLS, and IL-1β stimulation increased USP5 expression in a time-dependent manner." (PMID 32214906, 2020).